TXNDC5 (thioredoxin domain containing 5)
Diseases named in the same sentence as TXNDC5 in open-access papers (continued):
Sharing a sentence is not in itself a finding about the gene and the disease.
colorectal cancer (8 papers, 2017 to 2024). A primary or metastatic malignant neoplasm that affects the colon or rectum. "Previous studies validated that colorectal cancer tissues overexpress TXNDC5, and this overexpression is associated with poor clinical pathological characters in vivo." (PMID 39275334, 2024). "Hypoxia causes TXNDC5 expression by increasing hypoxia inducible factor-1α in vivo, thereby suppressing hypoxia-stimulated ROS/ER stress signaling and elevating the reproduction and survival of colorectal cancer cells." (PMID 39275334, 2024). "Under hypoxia, TXNDC5 performs as a prominent stress survival factor to induce the tumorigenesis of colorectal cancer by adjusting hypoxia-induced ROS/ER stress signaling." (PMID 39275334, 2024). "It has been demonstrated in various studies that Txndc5 is overexpressed in laryngeal squamous carcinoma cells, colorectal cancer cells, and liver and kidney cells under circumstances of ER stress." (PMID 39000233, 2024). "This study presents evidence that parecoxib enhances the anti-cancer power of resveratrol in DLD-1 colorectal cancer cells via the inhibition of TXNDC5 and Akt signaling and enhancement of JNK/p38 MAPK pathways." (PMID 39275334, 2024). "Hypoxia can inhibit hypoxia-induced ROS/ER stress signaling and promote proliferation and clone formation in colorectal cancer cells by inducing TXNDC5 overexpression through the upregulation of HIF-1α." (PMID 38629066, 2024). "Under hypoxic conditions, colorectal cancer cells showed increased apoptotic rates with TXNDC5 knockdown." (PMID 36106447, 2022). "TXNDC5 abnormally appeared in several cancers, such as colorectal cancer." (PMID 39275334, 2024). "In addition, several experiments have demonstrated that TXNDC5 is overexpressed in colorectal cancer tissues, revealing that TXNDC5 is a tumor-enhancing gene that promotes the proliferation and migration of a variety of tumor cells." (PMID 38629066, 2024). "TXNDC5 expression is induced under hypoxic conditions in disease states, such as RA, non-small cell lung cancer, and colorectal cancer, and also enhanced expression of TXNDC5 promotes the redox-sensitive activation of cardiac fibroblasts and the augmentation of cardiac fibrosis." (PMID 38666927, 2024). "In vivo studies showed that hypoxia induces TXNDC5 expression by upregulating hypoxia inducible factor-1α (HIF-1α), thereby inhibiting hypoxia-induced ROS/ER stress signalling and promoting the reproduction and survival of colorectal cancer (CRC) cells." (PMID 35934705, 2022). "However, no studies have evaluated the role of TXNDC5 or its related mechanisms on the combination of parecoxib and resveratrol on human colorectal cancer cells." (PMID 39275334, 2024). "Moreover, an in vitro study showed that hypoxia provokes TXNDC5 production by upregulating HIF-1α; this consequence may elevate the survival and proliferation of colorectal cancer cells in a hypoxia environment." (PMID 39275334, 2024).
lung carcinoma (8 papers, 2014 to 2024). "It is noteworthy that the knockdown of TXNDC5 sensitizes human lung cancer cells to ER stress-induced cell death, inhibits cell proliferation, and represses anchorage-independent colony formation and migration." (PMID 38666927, 2024). "TXNDC5 interacts with Srx to promote the retention of Srx in the ER, thereby protecting ER homeostasis of lung cancer cells and promoting the growth, proliferation, and invasion of cells." (PMID 35934705, 2022). "Further research indicated that the Srx-TXNDC5 complex may be used to predict the survival probability for lung cancer patients and as a therapeutic target or molecular diagnostic tool in human lung cancer pathogenesis." (PMID 38629066, 2024). "In addition, the content of TXNDC5 in relatively early stage lung cancer is higher than that in normal tissue." (PMID 35934705, 2022). "In lung cancer cells, TXNDC5 exerts a cancer-promoting effect by combining with sulfiredoxin (Srx)." (PMID 35934705, 2022). "In fact, TXNDC5 mRNA and protein expression has been found to be increased in cervical, uterine, colon, stomach, prostate, liver and lung cancer, and the protein was significantly upregulated in colorectal adenoma and cancer as compared with TXNDC5 levels in normal mucosa." (PMID 25526565, 2014). "A study found that knocking down TXNDC5 along with SRXN1 reduced the time needed for splicing XBP1 and spliced XBP1, resulting in the decreased expression of HSPA5, and among the handful of proteins that interact with SRXN1, PRDX6, PDIA6, and TXNDC5 were identified in lung cancer." (PMID 38666927, 2024).
atherosclerosis (7 papers, 2022 to 2024). A disease characterized by the build-up of fatty material and calcium deposition in the arterial wall resulting in partial or complete occlusion of the arterial lumen. "Recent evidence has found that in vivo deletion of Txndc5 in endothelial cells has been shown to increase endothelial nitric oxide synthase protein and reduce atherosclerosis in Apoe-deficient mice." (PMID 35327511, 2022). "We engineered global and endothelium-specific Txndc5 knockout mouse lines showing that Txndc5 deletion, particularly in vascular endothelium, causatively reduces atherosclerosis in vivo." (PMID 35061532, 2022). "Here, we engineered multiple transgenic mouse lines to demonstrate the causal role of endothelial Txndc5 in eNOS protein reduction and atherosclerosis." (PMID 35061532, 2022). "Here, we provided experimental evidence demonstrating a previously unidentified causal role of DF-induced endothelial TXNDC5 (thioredoxin domain containing 5) in atherosclerosis." (PMID 35061532, 2022). "To determine whether TXNDC5 causatively drives atherosclerosis in vivo, we then engineered a new mouse line [Txndc5−/−::ApoE−/− (DKO)] in which Txndc5 is globally deleted in the background of ApoE−/− mice." (PMID 35061532, 2022). "TXNDC5 was found enriched in endothelial cells (ECs) and fibroblasts, where TXNDC5 dysregulation was implicated in multiple diseases, including organ fibrosis, atherosclerosis, diabetes, liver disease, rheumatoid arthritis (RA), cancer, neurodegenerative disease and vitiligo." (PMID 36050716, 2022). "Their further studies found that TXNDC5 deletion in vascular endothelium result in increased eNOS protein and reduced atherosclerosis in apoE −/− mice." (PMID 38629066, 2024). "To determine a possible role of TXNDC5 in atherosclerosis, we analyzed the expression level of TXNDC5 in the atherosclerotic arterial tissues from both humans and mice." (PMID 35061532, 2022). "Targeting flow-sensitive TXNDC5, an ER protein driving endothelial dysfunction by destabilizing eNOS, lessens atherosclerosis." (PMID 35061532, 2022). "Here, we reported a critical yet previously unrecognized role of TXNDC5 in DF-induced endothelial activation and atherosclerosis." (PMID 35061532, 2022). "Supported by complementary in vitro and in vivo results, here we elucidate a new mechanosensitive molecular action of TXNDC5 to destabilize eNOS protein and drive DF-induced atherosclerosis." (PMID 35061532, 2022). "Our in vitro and in vivo results collectively demonstrate that mechanosensitive TXNDC5 is a previously unrecognized but key regulator of endothelial activation and atherosclerosis by destabilizing eNOS protein." (PMID 35061532, 2022). "Endothelial TXNDC5-dependent eNOS protein regulation and atherosclerosis in vivo were demonstrated using new transgenic mouse lines and supported by increased TXNDC5 expression detected in human atherosclerotic lesions." (PMID 35061532, 2022). "Endothelial Txndc5 deletion markedly reduces DF-induced atherosclerosis and plaque formation in hyperlipidemic mice." (PMID 35061532, 2022). "Nanoparticle-delivered, CRISPR-Cas9–mediated endothelial Txndc5 deletion significantly reduced atherosclerosis in mice." (PMID 35061532, 2022). "High expression of TXNDC5 can promote the progression of cancer, RA, fibrosis, atherosclerosis and other diseases." (PMID 35934705, 2022). "TXNDC5 deletion markedly increased eNOS protein and reduced atherosclerosis in ApoE −/− mice." (PMID 35934705, 2022). "Endothelium-specific Txndc5 deletion markedly reduced atherosclerosis in ApoE−/− mice." (PMID 35061532, 2022). "For example, a recent study demonstrated that inhibition of endothelial mechanosensitive protein, TXNDC5, reduces atherosclerosis without affecting plasma cholesterols." (PMID 37163513, 2023).
atherosclerosis (continued). "Moreover, nanoparticles formulated to deliver Txndc5-targeting CRISPR-Cas9 plasmids driven by an endothelium-specific promoter (CDH5) significantly increase eNOS protein and reduce atherosclerosis in ApoE−/− mice." (PMID 35061532, 2022). "Although TXNDC5 is highly expressed in vascular endothelium and therefore also known as Endo-PDI, it has never been investigated in the context of endothelial dysfunction or atherosclerosis." (PMID 35061532, 2022). "Although TXNDC5 was first cloned in human umbilical vein ECs, the role of endothelial TNXDC5 in mechanotransduction and atherosclerosis has not been reported previously." (PMID 35061532, 2022). "However, how the absence of TXNDC5 may influence SAA regulation under more stressful conditions like non-alcoholic fatty liver disease, fibrosis or atherosclerosis remains unclear." (PMID 35327511, 2022).
diabetes (7 papers, 2014 to 2025). "TXNDC5 has long been considered a gene that contributes to diabetes susceptibility (table in Section 8)." (PMID 38666927, 2024). "It has been reported that both high and low levels of TXNDC5 expression are associated with multiple diseases, such as arthritis, cancer, diabetes, brain diseases, and infections, as well as worse prognoses." (PMID 38666927, 2024). "As TXNDC5 helps in correct insulin folding, when its concentration decreases in pancreatic islets, the amount of insulin is reduced, causing diabetes, so TXNDC5 has a central role in glucose toxicity." (PMID 25526565, 2014). "In addition, TXNDC5 is strongly associated with a variety of diseases, such as diabetes, fatty liver, schizophrenia, and NSV." (PMID 38629066, 2024). "TXNDC5 and its associated genes in rheumatoid arthritis, diabetes mellitus and heart diseases." (PMID 38666927, 2024). "asserted that TXNDC5 induces insulin resistance and increases the risk of diabetes mellitus (DM) by inhibiting the expression of insulin-like growth factor binding protein-1 (IGFBP1)." (PMID 38629066, 2024). "High expression of TXNDC5 is a key factor in the development of inflammation, cancer, rheumatoid arthritis, organ fibrosis, diabetes and other diseases." (PMID 38629066, 2024). "While TXNDC5 dysregulation has been shown in multiple diseases, such as sepsis, rheumatoid arthritis, diabetes and cancers, by regulating inflammatory factors, emerging evidence demonstrated that TXNDC5 acts as a key pathogenic factor in organ fibrosis, including heart, lung, kidney and liver." (PMID 40261983, 2025). "TXNDC5 also protects pancreatic cells from palmitic acid-induced apoptosis by decreasing ER stress response, so it has potential to become a new pharmacological anti-diabetes target." (PMID 25526565, 2014). "For instance, TXNDC5’s interactions with NENF, PPP1R2, ALDOC, LDH, or PGD may help explain its relevance in diabetes." (PMID 38138960, 2023). "TXNDC5 interactions with NENF, PPP1R2, ALDOC, LDH, or PGD could explain its implication in diabetes." (PMID 25526565, 2014).
pancreatic cancer (7 papers, 2014 to 2024). "In pancreatic cancer, NR4A1 (Nur77, TR3) regulates TXNDC5 expression, maintains low levels of stress by ROS in cancer cells, and promotes pancreatic cancer cell proliferation." (PMID 38629066, 2024). "Moreoever, under elevated ER stress conditions, NRD4A1 driven cell survival was shown to be mediated through TXNDC5 in a pancreatic cancer setting." (PMID 36106447, 2022). "Inhibiting TXNDC5 expression via knockdown has previously been shown to induce ROS and ER stress in pancreatic cancer cells; however, increasing TXNDC5 expression in lipid endothelial cells effectively reduces ROS production and protects cells." (PMID 35326231, 2022). "The nuclear receptor 4A1 (NR4A1) in pancreatic cancer cells can promote the expression of the TXNDC5 gene to resist ROS/ER stress and inhibit cell apoptosis." (PMID 35934705, 2022). "Both IDH1 and TXNDC5 are regulated by NR4A1 in pancreatic and colon cancer cells, and knockdown of either NR4A1 or TXNDC5 in pancreatic cancer cells results in the induction of ROS." (PMID 27144436, 2016). "NR4A1 showed coordinate regulation with redox sensitive genes, e.g., TXNDC5, suggesting NR4A1 may regulate oxidative stress as has been observed in pancreas cancer models." (PMID 25538889, 2014).
rheumatoid arthritis (7 papers, 2011 to 2025). A chronic, systemic autoimmune disorder characterized by inflammation in the synovial membranes and articular surfaces. "TXNDC5 accompanied by multiple genes (table in Section 8) are key players in ER stress associated with synovitis in osteoarthritis, chronic pyrophosphate arthropathy, and rheumatoid arthritis." (PMID 38666927, 2024). "MiRNA-573 is another miRNA that can affect signaling pathways by downregulating TXNDC5 in the synovial tissue and fluids of rheumatoid arthritis (RA) patients." (PMID 38666927, 2024). "Our previous study detected increased TXNDC5 expression in the synovial tissues of rheumatoid arthritis (RA) patients using proteomic methods." (PMID 21801346, 2011).
esophageal squamous cell carcinoma (5 papers, 2019 to 2024). Esophageal squamous cell carcinoma (ESCC) is a type of esophageal carcinoma (EC) that can affect any part of the esophagus, but is usually located in the upper or middle third. "Human ether a-go-go-related gene 1 (HERG1) in esophageal squamous cell carcinoma (ESCC) can promote the expression of TXNDC5 and promote cancer progression by activating the PI3K/AKT pathway." (PMID 35934705, 2022). "Esophageal squamous cell carcinoma (ESCC) is a highly aggressive and lethal malignancy worldwide that KCNH2 contributes to the poor prognosis of ESCC by promoting ESCC cell proliferation, migration, and invasion via TXNDC5 through PI3K and AKT phosphorylation." (PMID 38666927, 2024).
non-small cell lung carcinoma (5 papers, 2014 to 2024). A group of at least three distinct histological types of lung cancer, including non-small cell squamous cell carcinoma, adenocarcinoma, and large cell carcinoma. "TXNDC5 is upregulated in several cancers such as hepatocellular, breast, cervical, colon, esophageal, liver, lung, stomach and uterine carcinomas, in colorectal cancer, in non-small cell lung carcinoma and renal tumor tissue." (PMID 25526565, 2014). "For example, in non-small cell lung carcinoma, hypoxia does not change TXNDC5 expression, leaving an open horizon to better characterize its regulation." (PMID 25526565, 2014).
renal cell carcinoma (5 papers, 2014 to 2024). "Regarding to renal cell carcinoma (RCC), the ratio of TXNDC5/AdipoR1 expression was significantly higher in metastatic renal cell carcinoma tissues than in nonmetastatic controls." (PMID 38629066, 2024).
gastric adenocarcinoma (4 papers, 2015 to 2024). "In the current study, the expression of the TXNDC5 gene in gastric adenocarcinoma tissues was detected using immunohistochemistry, and the association between TXNDC5 expression and clinicopathological features was analyzed." (PMID 25663872, 2015). "Furthermore, the association between TXNDC5 expression and clinicopathological factors in gastric adenocarcinoma remains unclear." (PMID 25663872, 2015). "In the present study, the immunohistochemical expression and clinicopathological significance of TXNDC5 in gastric adenocarcinoma was investigated." (PMID 25663872, 2015). "In the present study, the expression of TXNDC5 in gastric adenocarcinoma was investigated by immunohistochemistry and the clinicopathological significance of TXNDC5 gene expression was investigated." (PMID 25663872, 2015). "The results indicated that the TXNDC5 gene was expressed in gastric adenocarcinoma and that the positive signals were predominantly located in the cytoplasm of the tumor cells." (PMID 25663872, 2015). "The immunohistochemical expression of TXNDC5 was detected in 54 gastric adenocarcinoma specimens, and the correlation between TXNDC5 and the clinicopathological features was investigated." (PMID 25663872, 2015). "Of the 54 gastric adenocarcinoma specimens, 30 samples (55.6%) exhibited high TXNDC5 expression." (PMID 25663872, 2015). "Therefore, the expression of TXNDC5 may correlate with the differentiation, invasion and metastasis of gastric adenocarcinoma." (PMID 25663872, 2015). "However, the involvement of TXNDC5 in gastric adenocarcinoma remains unclear." (PMID 25663872, 2015).
schizophrenia (4 papers, 2011 to 2024). A major psychotic disorder characterized by abnormalities in the perception or expression of reality. "A SNP (rs13873) in the TXNDC5 gene and haplotype rs1225934-rs13873 in BMP6-TXNDC5 play a role in the selective impairment of persistent attention disorder in schizophrenia." (PMID 38629066, 2024). "The rs13873 SNP of the TXNDC5 gene and the rs1225934–rs13873 haplotype of the BMP6–TXNDC5 gene are related to sustained attention impairment in patients with schizophrenia." (PMID 35934705, 2022). "Some TXNDC5 polymorphisms (rs13873) and BMP6-TXNDC5 polymorphisms (rs1225934, rs13873) are significantly related to schizophrenia due to a deficit in cluster 1, while cluster 2 is not modified." (PMID 25526565, 2014). "Loss of TXNDC5 function could promote APP misfolding and, consequently, play a key role in neurodegenerative diseases; moreover, its interaction with the zinc finger XNF706 could be involved in schizophrenia." (PMID 25526565, 2014).
vitiligo (4 papers, 2011 to 2022). Generalized well circumscribed patches of leukoderma that are generally distributed over symmetric body locations and is due to autoimmune destruction of melanocytes. "A total of 230 Korean patients with non-segmental vitiligo were investigated for SNPs in the TXNDC5 gene; in total, seven SNPs were identified in the TXNDC5 gene, three of which (rs1043784, rs7764128, and rs8643) demonstrated an association with the vitiligo phenotype." (PMID 23245351, 2012).
Arthritis (3 papers, 2013 to 2024). Inflammation of a joint. "TXNDC5 overexpression may overcome the H-2q allele to induce arthritis in C57 mice." (PMID 23326410, 2013). "Transgenic mice that over-expressed TXNDC5 (TXNDC5-Tg) were generated using C57BL/6J mice and treated with bovine collagen II to induce arthritis (CIA)." (PMID 23326410, 2013).
colon cancer (3 papers, 2016 to 2023). "It should also be noted that there were colon cancer cell context-dependent differences in the effects of piperlongumine on downregulation of IDH-1 and TXNDC5." (PMID 37808182, 2023). "Treatment of the colon cancer cells with piperlongumine resulted in downregulation of IDH1 in RKO, SW480, and HCT116 (not significant) cells and selective downregulation of TXNDC5 in only SW480 cells." (PMID 37808182, 2023).